SPACA1 (sperm acrosome associated 1)
Description:
Plays a role in acrosome formation and establishment of normal sperm morphology during spermatogenesis. Important for male fertility.
Synonyms: SAMP32; SPGF85
Tractability: Antibody: UniProt predicts a signal peptide or a membrane-spanning region.
Gene: Protein-coding gene on chromosome 6 (88,047,841 to 88,066,838, forward strand). Ensembl gene ENSG00000118434.
Subcellular location: Cytoplasmic vesicle, secretory vesicle, acrosome inner membrane
Subcellular location (Human Protein Atlas): Acrosome
Gene Ontology:
Molecular function: protein binding
Biological process: acrosome assembly
Cellular component: acrosomal vesicle; acrosomal membrane; inner acrosomal membrane
Genetic constraint (gnomAD): Loss-of-function variants: 14 observed, 21.78 expected, observed/expected ratio (o/e) 0.64, 90% interval 0.42 to 1. The upper end of that interval is the gene's LOEUF score, 1, which puts it in group 4 of 6, group 1 being the genes least tolerant of losing a copy. Missense variants: 325 observed, 321.82 expected, observed/expected ratio (o/e) 1.01, 90% interval 0.92 to 1.11. Synonymous variants: 129 observed, 118.35 expected, observed/expected ratio (o/e) 1.09, 90% interval 0.94 to 1.26.
Homologues: Orthologues: chimpanzee SPACA1 (96% identical), macaque SPACA1 (93% identical), rabbit SPACA1 (78% identical), dog SPACA1 (76% identical), pig SPACA1 (75% identical), rat Spaca1 (71% identical), mouse Spaca1 (70% identical), guinea pig SPACA1 (67% identical).
Diseases named in the same sentence as SPACA1 in open-access papers:
SPACA1 is named in the same sentence as 4 diseases in open-access papers, as found by Europe PMC text mining. Sharing a sentence is not in itself a finding about the gene and the disease. The quoted sentences say what the papers report.
Globozoospermia (11 papers, 2015 to 2025). Any structural anomaly of the acrosome resulting in a round sperm head. "SPACA1-deficient male human and mice are infertile with abnormally shaped sperm heads reminiscent of globozoospermia." (PMID 33231562, 2020). "Studies of spermatogenesis have identified many acrosome-associated genes, such as Zpbp1, Spaca1, and Spata46 as causes of globozoospermia." (PMID 32301969, 2020). "In gene KO mouse studies, various genes (Atg7, Csnk2a2, Dpy19l2, Gba2, Golga2, Gopc, Hrb, Hsp90b1, Mfsd14a, Pick1, Sirt1, Slc9a8, Smap2, Spaca1, Tmf1, Vps54, Zpbp1) were found to be associated with globozoospermia." (PMID 29065458, 2017). "Sperm acrosome associated 1 (Spaca-1) has recently been found to be a new member of the globozoospermia-related genes." (PMID 26436098, 2015). "SPACA1-deficient mice show a globozoospermia-like phenotype and infertility." (PMID 38597936, 2024). "SPACA1 gene-disrupted male mice were infertile and showed abnormal shaping of spermatozoa leading to globozoospermia." (PMID 35286314, 2022). "Although other KO mice with a globozoospermia-like phenotype showed a significant reduction of testicular SPACA1, SPACA1 remained in the Spata16−781/−781 mouse testis." (PMID 29065458, 2017). "Next, the onset of Spata16 expression was examined by RT-PCR and compared with that of globozoospermia-related genes: Dpy19l2, Pick1, and Spaca1." (PMID 29065458, 2017). "Testicular SPACA1 is essential for acrosomal formation and is a downstream factor of the other globozoospermia-related proteins." (PMID 29065458, 2017). "Spaca1-KO mice displayed phenotypesassociated with globozoospermia, specifically a lack of an acrosome.Interestingly, Zpbp1-KO mice also lacked SPACA1 protein." (PMID 40833973, 2025). "Because the amount of testicular SPACA1 only slightly reduced in Spata16−781/−781 mice, we can assume that mouse SPATA16 is not related to globozoospermia." (PMID 29065458, 2017).
infertile (5 papers, 2015 to 2024). "SPACA1 deficient mice are infertile and show abnormally shaped sperm heads." (PMID 26221191, 2015). "It has been reported that disruption of SPACA1 leads to infertility due to abnormal sperm head shape and abnormal acrosomes in sperm, and GSK3A-deficient mice show bent sperm heads, similar to the phenotype of Ccdc28a−/− mice." (PMID 38597936, 2024). "Knockout of the Spaca1 gene leads to a deformed sperm head, resulting in infertility in mice." (PMID 36624393, 2023). "These indices were highly correlated with the results of conventional IVF (developmental rates of embryos to blastocysts), suggesting that the SPACA1 indices could be valid as biomarkers that can predict the effectiveness of conventional IVF for human infertile patients." (PMID 29259456, 2017). "According to investigations of human spermatozoa from infertile patients, human SPACA1 proteins might not be tyrosine‐phosphorylated, unlike bovine SPACA1 proteins." (PMID 29259456, 2017).
male infertility (4 papers, 2020 to 2025). The inability of the male to effect fertilization of an ovum after a specified period of unprotected intercourse. "Loss of SPACA1 and ACTL7A induce abnormal acrosome formation in spermatogenesis and male infertility." (PMID 38597936, 2024).
SPACA1 also shares sentences with these, for which no sentence is quoted: seminoma (1 paper).